TRPA1 (transient receptor potential cation channel subfamily A member 1)
Diseases named in the same sentence as TRPA1 in open-access papers (continued):
Sharing a sentence is not in itself a finding about the gene and the disease.
depression (13 papers, 2019 to 2025). "In the future, we plan to test the effect of DMTS in the unpredictable mild stress mouse model of depression to explore other background mechanisms besides the TRPA1 ion channel in mediating the effect of DMTS." (PMID 39062944, 2024). "We applied the widely used and well-characterized CVMS model of depression in Trpa1 KO and WT mice." (PMID 38339042, 2024). "Moreover, it is known that TRPA1 agonists in the hippocampus lead to the depressive-and anxiolytic-like effects, while pharmacological blockage or TRPA1 gene deletion reduce the depression-and anxiolytic-like symptoms." (PMID 36533180, 2022). "Therefore, DNA methylation of the TRPA1 is unlikely a confounder for pain intensity or depression in neuropathic pain states." (PMID 32080151, 2020). "Another study, done by the same group aimed to explore the probable mechanism of TRPA1 involvement in depression, revealed that intracerebroventricular (ICV) perfusion of TRPA1 antibody in rats led to inhibition of CSD." (PMID 34912298, 2021). "Secondly, we proposed to investigate if the response to the CVMS model of depression is affected by a lack of functional TRPA1." (PMID 38339042, 2024). "The Trpa1 mRNA expression was confirmed by our research group in both the mouse and human EWcp, which was downregulated in both mice exposed to the chronic variable mild stress (CVMS) model of depression and in depressed human suicide victims." (PMID 38339042, 2024). "We investigated TRPA1 knockout and wildtype mice using the CVMS model of depression." (PMID 38339042, 2024). "In our previous study we also found that the lack of functionally active TRPA1 affected the UCN1 content both in models of depression and posttraumatic stress disorder." (PMID 36704197, 2022). "In accordance with the human findings and using the CVMS model of depression in mice, we demonstrated that the UCN1 peptide content was increased while the level of Trpa1 mRNA was downregulated in EWcp neurons upon stress, further supporting the regulatory role of TRPA1 in stress adaptation." (PMID 38339042, 2024).
prostate carcinoma (13 papers, 2018 to 2025). A carcinoma that arises from epithelial cells of the prostate gland. "TRPA1 is highly expressed in pancreatic adenocarcinoma, nasopharyngeal carcinoma, and prostate cancer-associated fibroblast cell cultures." (PMID 38612571, 2024). "TRPA1 has been described to be upregulated in different tumors, such as nasopharyngeal carcinoma, pancreatic adenocarcinoma and prostate cancer-associated fibroblast cell cultures." (PMID 35163843, 2022). "In prostate cancer-associated fibroblasts, activation of TRPA1 leads to increased Ca2+ levels and elevated hepatocyte growth factor (HGF) and vascular endothelial growth factor (VEGF) secretion." (PMID 29772843, 2018). "Additionally, the TRPA1 protein was expressed and mediated an increase in the intracellular Ca2+ concentration ([Ca2+]i) in human prostate cancer-associated fibroblasts (CAFs)." (PMID 37174661, 2023). "A study in prostate cancer CAFs identified that TRPA1 activation by resveratrol leads to strong Ca2+ cytosolic influx and secretion of VEGF and HGF." (PMID 40640495, 2025). "Copy number alterations were also observed rarely with the exception of the amplification of TRPA1, which was amplified in 7.2% of prostate cancers in TCGA, and of TRPC4 and TRPC3, which were homodeleted in 5.9% and 2.5% of cases, respectively." (PMID 40332161, 2025). "In the same study, activation of TRPA1 in a co-culture model reduced prostate cancer cell death by 40%." (PMID 40640495, 2025). "For instance, in oral squamous cell carcinoma, the TRPA1 channel is overexpressed, and the activation of TRPA1 can promote the metastasis and proliferation of prostate cancer cells." (PMID 36090899, 2022). "An in vitro study that focused on the interactions between prostate cancer cells and CAFs identified that resveratrol activates the TRPA1 calcium channel in CAFs and leads to a strong Ca2+ influx and secretion of VEGF and HGF." (PMID 34768796, 2021). "Like resveratrol, TCS can induce TRPA1-mediated Ca2+ influx in prostate cancer-derived CAFs, leading to increased secretion of VEGF." (PMID 34768796, 2021). "Similarly, in the MSK cohort, TRPA1 was amplified in 6.3% of prostate cancers and TRPC4 and TRPC3 were homodeleted in 4.4% and 1.5% of cases, respectively." (PMID 40332161, 2025). "Therefore, it is important to stratify prostate cancer patients based on their TRPA1 types and apply RSV only to those with wild-type TRPA1." (PMID 33535458, 2021). "TRPA1 activation significantly reduces prostate cancer cell death by 40% in a co-culture model." (PMID 34768796, 2021). "Co-cultured prostate cancer cells are rescued from apoptosis by TRPA1 activation." (PMID 29772843, 2018). "This study showed that the antibacterial agent, triclostan, stimulated TRPA1 to mediate extracellular Ca2+ entry, thereby resulting in vascular endothelial growth factor (VEGF) secretion and prostate cancer cell proliferation." (PMID 37174661, 2023). "Use of HC-030031, a TRPA1 inhibitor, significantly reduced the Ca2+ influx and VEGF and HGF secretion in CAFs and blocked the protective effect on prostate cancer." (PMID 34768796, 2021). "Of note, this same study also noticed that RSV can exert an opposite effect on cells expressing a mutant TRPA1, which not only increased expression and secretion of HGF and VEGF, but also enhanced prostate cancer metastasis." (PMID 33535458, 2021). "TRPA1 protein is up-regulated in multiple solid malignancies, such as invasive ductal breast carcinoma and lung adenocarcinoma, OSCC, pancreatic adenocarcinoma, and prostate cancer." (PMID 37393347, 2023). "Similarly, TRPA1 was expressed in prostate cancer stromal cells expanded from different patients, but not in healthy primary cultured prostate epithelial cells." (PMID 37174661, 2023).
prostate carcinoma (continued). "TRPA1 activation might also promote prostate cancer progression by triggering prostate cancer stromal cells’ secretion of VEGF, a known mitogenic factor involved in the proliferation, migration and invasion of prostate cancer cells." (PMID 35806388, 2022). "In prostate CAFs, TRPA1 could be activated by the natural polyphenolic antioxidant, resveratrol, and induced the secretion of VEGF and hepatocyte growth factor (HGF), which in turn reduced resveratrol-induced apoptosis in co-cultured human prostate cancer cells." (PMID 37174661, 2023).
rheumatoid arthritis (13 papers, 2015 to 2024). A chronic, systemic autoimmune disorder characterized by inflammation in the synovial membranes and articular surfaces. "TRPA1 has been implicated in joint pain and inflammation associated with rheumatoid arthritis TRPA1." (PMID 39022308, 2024). "Activation of TRPA1 by polygodial in rheumatoid arthritis FLS led to necrosis of the cells and reduced proliferation." (PMID 35745590, 2022). "Modulation of nociception and inflammation by sulfide in rheumatoid arthritis and activation of transient receptor potential ankyrin 1 (TRPA1) ion channels by sulfide compounds are well documented." (PMID 31551776, 2019). "Increased expression of TRPA1 was reported in peripheral blood leukocytes of rheumatoid arthritis patients." (PMID 31551776, 2019). "Although TRPA1 expression in immune cells is still controversial, it has been demonstrated that TRPA1 amount on peripheral blood leukocytes correlates with pain severity and disability in rheumatoid arthritis, suggesting a role in inflammatory responses." (PMID 34065398, 2021). "In rheumatoid arthritis synovial fibroblasts, the expression of TRPV1 and TRPA1 and the regulation of related receptors by endogenous agonists have been shown to reduce the production of IL-6, IL-8 and MMP-3." (PMID 36278189, 2022). "Synovial fibroblasts are affected by rheumatoid arthritis, and the cytokine TNF upregulates TRPA1, the activation of which can increase the intracellular calcium level, leading to lactate dehydrogenase release." (PMID 36278189, 2022). "According to research, TRP channels have become drug targets for the treatment of RA as there are multiple TRP channels in rheumatoid arthritis synovial fibroblasts, including TRPV1, TRPA1, TRPC5, TRPM3, TRPM7, and TRPM8." (PMID 30792744, 2019). "TRPs are also involved and upregulated in rheumatoid arthritis (RA) where the preincubation of synovial fibroblasts with TNF upregulated and sensitized TRPA1, reducing cell viability by inducing necrosis." (PMID 31197115, 2019). "Similar effects of CBD under inflammatory conditions connected with rheumatoid arthritis development are observed in synovial fibroblasts, where CBD decreases MMP-3 level by activating transient receptor potential ankyrin (TRPA1), and increasing intracellular calcium levels." (PMID 34691360, 2021).
endometriosis (12 papers, 2014 to 2025). The growth of functional endometrial tissue in anatomic sites outside the uterine body. "A significant increase in the TRPA1 mRNA content was observed in nociceptive neurons in the peritoneum of women with chronic pelvic pain caused by endometriosis." (PMID 35562920, 2022). "Increased immunoreactivity of TRPA1, associated with increased mRNA expression in ectopic endometrium of deep infiltrating endometriosis patients, has been detected." (PMID 35562920, 2022). "mRNA encoded by TRPA1 was significantly increased in the peritoneum of women with endometriosis compared with the peritoneum of healthy women and those with CPP alone (P < .001)." (PMID 25029427, 2014). "The neuropeptide substance P (encoded by the TAC1 gene) has been immunolocalized to endometriosis lesions, and TRPA1 has been implicated in thermal and mechanical hypersensitivity to pain." (PMID 25029427, 2014). "The role of TRPA1 as a major sensor and amplifier of the oxidative burst underlying a variety of inflammatory responses supports its implication in endometriosis pain symptoms." (PMID 35562920, 2022). "Formation of TRPV1/TRPA1 heteromeric calcium channels promotes the sensitization of peripheral nerve endings and enhances pain intensity in endometriosis." (PMID 39056769, 2024). "An increase in TRPA1 mRNA and exaggerated Ca2+ responses in dorsal root ganglion (DRG) neurons from mice with endometriosis has been reported, suggesting that endometriosis affects protein expression and TRPA1 responsiveness in DRG neurons." (PMID 35562920, 2022). "The severity of the endometriosis (including symptoms as dysmenorrhea, dyspareunia and dyschezia) correlates with exacerbated expression of TRPA1 and TRPV1 channels, suggesting that these channels play a role in this disease." (PMID 32471309, 2020). "The mRNA concentration of transient receptor potential vanilloid 1 (TRPV1) and transient receptor potential cation channel, subfamily A, member 1 (TRPA1) are significantly higher in women with endometriosis." (PMID 30518376, 2018). "We believe this is the first study to detect differences in the expression of mRNAs encoded by the ion channels TRPA1, P2RX3, SCN9A, and SCN11A in the peritoneum and lesions of women suffering from CPP, some of whom had endometriosis." (PMID 25029427, 2014). "In women with active endometriosis, we discovered that the concentrations of mRNAs encoded by SCN11A, TRPA1, and TRPV1 were all significantly increased in the samples of peritoneum." (PMID 25029427, 2014). "Moreover, endometrium samples from women with the most severe form of endometriosis, such as deep infiltrating endometriosis, display higher TRPA1 and TRPV1 expression than the samples from healthy women." (PMID 32471309, 2020). "Furthermore, peritoneal biopsies from women with endometriosis display upregulation in the mRNA levels for TRPA1 and TRPV1, indicating that the pain produced in this pathology could be associated with the overexpression of these pain mediators." (PMID 32471309, 2020). "TRPV1, TRPA1, and SCN11A mRNAs were significantly higher in the peritoneum from women with endometriosis (P < .001, P < .01)." (PMID 25029427, 2014). "In a non-surgical model of endometriosis, the presence of TRPA1 was found in endometriotic lesions infiltrated with macrophages, neutrophils, and mast cells." (PMID 35562920, 2022). "In addition, an elevation of TRPA1 mRNA expression levels was reported in peritoneal tissue of endometriosis, but not within the endometriosis lesions." (PMID 41154581, 2025). "In summary, the results of this study indicate that therapies targeting P2RX3 may be useful in treating CPP in women with a diverse range of painful etiologies, whereas women with active endometriosis could benefit from treatments targeting TRPV1, TRPA1, SCN9A, or SCN11A." (PMID 25029427, 2014).
familial episodic pain syndrome (12 papers, 2012 to 2025). "In familial episodic pain syndrome, a missense mutation in the TRPA1 gene causes an amino acid substitution (Asp-858-Ser) that alters the functions of this ion channel." (PMID 32824721, 2020). "The TRPA1 gene is located on chromosome 8q21.11 (GRCh38.p12), and genetic variations in TRPA1 have been associated with various pain syndromes (e.g., familial episodic pain syndrome) and conditions (e.g., neuropathic and inflammatory pain)." (PMID 32824721, 2020). "The GOF mutation N855S in TRPA1 has been associated with familial episodic pain syndrome." (PMID 36430572, 2022). "A GOF point mutation in the transmembrane segment S4 of TRPA1 (N855S) causes the familial episodic pain syndrome (FEPS)." (PMID 29736621, 2018). "In terms of pain, humans with a gain-of-function mutation in the TRPA1 gene develop Familial Episodic Pain Syndrome (FEPS), a pain syndrome associated with enhanced sensitivity to noxious mechanical and chemical stimuli." (PMID 29084244, 2017). "Recently, a TRPA1 gain of function mutation was linked to human congenital pain condition called familial episodic pain syndrome (FEPS)." (PMID 25640188, 2015). "For example, in Inherited Erythromelalgia (NaV1.7) or Familial Episodic Pain Syndrome (TRPA1, NaV1.9), sensory examination (between pain episodes), neurophysiology and cutaneous innervation are normal." (PMID 36895957, 2023). "In what is known as Familial Episodic Pain Syndrome (FEPS), a gain of function mutation of TRPA1 causes episodes of severe pain localized principally to the upper body that are triggered by cold, fasting or physical stress." (PMID 34068986, 2021). "Notably, the S4-S5 linker appears to be a hot-spot for mutations in several TRP channels, including TRPV3 (congenital Olmsted syndrome), TRPV4 (skeletal dysplasia, motor/sensory neuropathies), TRPA1 (familial episodic pain syndrome), and TRPML1 (mucolipidosis type IV)." (PMID 41005473, 2025). "Notably, Trpa1 (Transient Receptor Potential Cation Channel Subfamily A Member 1), a gene that is involved in familial episodic pain syndrome and other forms of nociceptive behavior, was highly upregulated in A/J mice, but only minor changes were induced by SCI in the other strains." (PMID 38727295, 2024). "Evidence for a pronociceptive role for TRPA1 is provided by genetic analysis of patients with familial episodic pain syndrome (FEPS)." (PMID 24278716, 2012).
gout (12 papers, 2015 to 2025). A condition characterized by painful swelling of the joints, which is caused by deposition of urate crystals. "In gouty arthritis, ROS generated by neutrophils in affected joints can directly activate TRPA1+ neurons, contributing to pain." (PMID 40370462, 2025). "In conclusion, TRPV1, TRPM2 and TRPA1 gene knockout or pharmacological inhibition can reduce joint pain and oedema in mice with gouty arthritis." (PMID 38659380, 2024). "IL-33 promoted neutrophil influx and triggered neutrophil-dependent ROS production via ST2 during gout, which in turn, activated transient receptor potential ankyrin 1 (TRPA1) channel in dorsal root ganglion (DRG) neurons and produced nociception." (PMID 33204337, 2020). "It is reported that TRPA1 expression is upregulated in the inflamed joint tissues of gout model mice." (PMID 33204337, 2020). "In all, our study demonstrated a previous unidentified role of IL-33/ST2 in mediating pain hypersensitivities and inflammation in a mouse gout model through promoting neutrophil-dependent ROS production and TRPA1 channel activation." (PMID 33204337, 2020). "We further found that IL-33/ST2 mediates pain hypersensitivity and inflammation in the mouse gout model through promoting neutrophil-dependent ROS production and TRPA1 channel activation." (PMID 33204337, 2020). "Additional evidence at room temperature in an MSU model of gouty arthritis also identified an increase in TRPA1 protein expression in both joint tissues and the skin." (PMID 30326593, 2018). "The findings concerning TRPA1’s involvement in gout are particularly strong and consistent, and future pharmaceutical development focusing on this channel are likely warranted." (PMID 30326593, 2018). "The present results propose TRPA1 as an attractive novel anti-inflammatory and analgesic drug target to treat acute gouty arthritis." (PMID 25658427, 2015). "Further, the results strongly suggest TRPA1 as a mediator and drug target to treat painful gout flares in man." (PMID 25658427, 2015). "TRPA1 mediates MSU crystal-induced inflammation and pain in experimental models supporting the role of TRPA1 as a potential mediator and a drug target in gout flare." (PMID 25658427, 2015). "Besides TRPA1 involvement in gout, TRPV1 channels are also described as important for gout pain and inflammation." (PMID 36173505, 2022). "However, given the success of TRPV1 agonists as topical treatments for OA, further studies on the effects of TRPA1 agonists for RA, OA, or gout are likely warranted." (PMID 30326593, 2018). "Indeed, blockade of TRPA1 reduces pain behaviors in response to injection of H2O2 in the MSU model of gout." (PMID 30326593, 2018). "Therefore, the enhanced TRPA1 channel functional activity we observed may be due to channel expression upregulation mediated by IL-1β, IL-6 or other inflammatory mediators released during gout." (PMID 33204337, 2020). "Further, TRPA1 channel activity was significantly enhanced in DRG neurons that innervate the inflamed ankle via ST2 dependent mechanism, which results in exaggerated nociceptive response to endogenous ROS products during gout." (PMID 33204337, 2020). "In the MSU model of gout, data indicate that secretion of neuropeptides and cytokines like CGRP, IL-1β, and IL-6 is reduced in the presence of HC-030031 and upon genetic deletion of TRPA1." (PMID 30326593, 2018). "These three studies beautifully complement and strengthen each other and highlight the previously unknown role of TRPA1 in the development of MSU crystal-induced inflammation and pain applicable for the pathogenesis and drug development for gout flare." (PMID 25658427, 2015). "TRPA1 was found to mediate MSU crystal-induced inflammation and pain in three different experimental models supporting the role of TRPA1 as a potential mediator and a drug target in gout flare." (PMID 25658427, 2015). "Therefore we hypothesized that TRPA1 may contribute to MSU crystal-induced inflammation and pain in gout flare." (PMID 25658427, 2015).
gout (continued). "In the present study we tested the hypothesis that Transient Receptor Poten-tial Ankyrin 1 (TRPA1), an ion channel mediating nociceptive signals and neurogenic in-flammation, is involved in MSU crystal-induced responses in gout by utilizing three experi-mental murine models." (PMID 25658427, 2015).